KIR3DL2 (killer cell immunoglobulin like receptor, three Ig domains and long cytoplasmic tail 2)
Description:
Receptor on natural killer (NK) cells and T cells for MHC class I molecules. Upon binding of peptide-free HLA-F open conformer, negatively regulates NK and T cell effector functions. Acts as a receptor on astrocytes for HLA-F. Through interaction with HLA-F, may protect motor neurons from astrocyte-induced toxicity.
Synonyms: NKAT-4; CD158k; NKAT4; cl-5; nkat4a; nkat4b; 3DL2; KIR-3DL2; p140
Tractability: Antibody: a drug acting on it is in phase 2 or 3 trials; its Gene Ontology location is reachable by antibodies, with high confidence; UniProt places it where antibodies can reach, with medium confidence; UniProt predicts a signal peptide or a membrane-spanning region. PROTAC: ubiquitination databases record sites on it.
Target class: Membrane receptor
Gene: Protein-coding gene on chromosome 19 (54,850,433 to 54,867,209, forward strand). Ensembl gene ENSG00000240403.
Subcellular location: Cell membrane
Pathways (Reactome):
Immune System: Immunoregulatory interactions between a Lymphoid and a non-Lymphoid cell
Gene Ontology:
Molecular function: MHC class Ib protein binding; protein binding; immune receptor activity; transmembrane signaling receptor activity
Biological process: cellular defense response; immune response-inhibiting cell surface receptor signaling pathway
Cellular component: plasma membrane
Genetic constraint (gnomAD): Loss-of-function variants: 42 observed, 42.33 expected, observed/expected ratio (o/e) 0.99, 90% interval 0.77 to 1.28. The upper end of that interval is the gene's LOEUF score, 1.28, which puts it in group 5 of 6, group 1 being the genes least tolerant of losing a copy. Missense variants: 728 observed, 579.04 expected, observed/expected ratio (o/e) 1.26, 90% interval 1.18 to 1.34. Synonymous variants: 230 observed, 216.95 expected, observed/expected ratio (o/e) 1.06, 90% interval 0.95 to 1.18.
Homologues: Orthologues: mouse Kir3dl1 (35% identical), mouse Kir3dl2 (34% identical), rat Kir3dl1 (33% identical), tropical clawed frog xilr1 (16% identical). Paralogues in human: KIR3DL1 (84% identical), KIR3DL3 (71% identical), KIR2DL1 (64% identical), KIR2DL3 (64% identical), KIR2DL4 (52% identical), LILRB1 (35% identical), LILRB2 (35% identical), LILRB3 (34% identical), KIR2DS4 (33% identical), LILRB5 (32% identical), LILRA6 (30% identical), LILRA1 (29% identical), and 13 more.
Diseases named in the same sentence as KIR3DL2 in open-access papers:
KIR3DL2 is named in the same sentence as 78 diseases in open-access papers, as found by Europe PMC text mining. Sharing a sentence is not in itself a finding about the gene and the disease. The quoted sentences say what the papers report.
COVID-19 (10 papers, 2022 to 2025). A disease caused by infection with severe acute respiratory syndrome coronavirus 2. "We observed that the KIR3DL1+HLA-Bw4+ and KIR3DL2+HLA-A3/11+ gene combinations were encountered at significantly lower frequency in COVID-19 patients than in the general population." (PMID 35273641, 2022). "Future mechanistic studies are warranted to confirm the molecular basis of the decreased KIR3DL1+HLA-Bw4+ and KIR3DL2+HLA-A3/11+ gene combinations in dampening the effector functions of NK cells in COVID-19 patients." (PMID 35273641, 2022). "Similarly, the frequency of the KIR3DL2+HLA-A3+ combination (11.5 vs. 26.1%, p = 0003, OR = 0.37, CI = 0.21–0.63) was significantly lower in COVID-19 patients than in the general population controls." (PMID 35273641, 2022). "Differential expression of NK cell receptor genes, such as KLRC2 and KIR3DL2 in CD16+ CD8+ TEMRA-2 cells in mild COVID-19 compared with severe COVID-19 further strengthened the hypothesis of profound differences in NK-like differentiation between disease conditions." (PMID 36591270, 2022). "Comparison between the disease conditions indicated significantly stronger expression of certain NK cell receptors (CD160, KLRC2, KLRC3, KLRF1, KIR3DL2, NCR1, NCR3) along the SLEC lineage in mild COVID-19 compared to severe COVID-19." (PMID 36591270, 2022). "KIR2DL1, KIR2DL3, KIR3DL1 and KIR3DL2 are inhibitory NK cell receptors and enhanced interactions via these receptors on CD8+ T cells could indicate a more balanced functional regulation of CD8+ T cells in mild COVID-19." (PMID 36591270, 2022). "Notably, 40% of the COVID-19 patients were negative for both KIR3DL1+HLA-Bw4+ and KIR3DL2+HLA-A3/11+ combinations compared to 24.6% of the general population (OR = 2.04, p = 0.001, CI = 1.33–3.14)." (PMID 35273641, 2022). "Presumably, the reduced antiviral defense due to the absence of KIR3DL1+HLA-Bw4+ and KIR3DL2+HLA-A3/11+ interactions coupled with exuberant hyperinflammatory response mediated by activating KIR2DS1 and 2DS5 arbitrate the development of severe COVID-19." (PMID 35273641, 2022).
autoimmune disease (8 papers, 2019 to 2024). A disorder resulting from loss of function or tissue destruction of an organ or multiple organs, arising from humoral or cellular immune responses of the individual to their own tissue constituents. "For example, iKIR expression by CD4+ T cells is increased in ankylosing spondylitis (1–6% of all CD4+ cells are KIR3DL2+, rising to 10–60% of Th17 CD4+ cells) and other autoimmune diseases such as lupus show similar increases in iKIR expression." (PMID 39724143, 2024). "Later, our group also demonstrated that reduced expression of the inhibitory KIR3DL2 protects against EPF, which is further evidence that NK cell activation is unusually protective for this autoimmune disease." (PMID 35632621, 2022).
Sézary syndrome (8 papers, 2012 to 2023). "Besides, KIR3DL2 was recently found to be the biomarker for Sezary syndrome, a potent type of cutaneous T-cell lymphoma." (PMID 36674212, 2023). "KIR3DL2 was reported as a sensitive diagnostic factor and also associated with reduced disease-specific survival for CD3+ T cells in peripheral blood of Sezary syndrome (SS), a leukemic form of cutaneous T cell lymphoma (CTCL) and expressed in 65.7% CTCL skin biopsies." (PMID 35652109, 2022). "Targeted treatment for Sézary syndrome, including anti-KIR3DL2 antibodies, may be applicable in this group of MF patients." (PMID 35241665, 2022). "KIR3DL2 (CD158k) from neoplastic cells is expressed as in Sezary syndrome." (PMID 32013101, 2020). "Moreover, KIR3DL2 expression delineates circulating and cutaneous lymphoma T cells in Sézary’s syndrome." (PMID 23162554, 2012). "KIR3DL2 (CD158K), a killer immunoglobulin-like receptor (KIR) normally expressed by a subset of natural killer (NK) cells is aberrantly expressed in Sezary syndrome and several other CTCLs." (PMID 32547515, 2020).
ankylosing spondylitis (5 papers, 2012 to 2025). An autoimmune chronic inflammatory disorder characterized by inflammation in the vertebral joints of the spine and sacroiliac joints. "KIR‐3DL2+CD4+ T cells in patients with ankylosing spondylitis were oligoclonal and enriched for markers of T cell activation and for the gut homing receptor CCR9." (PMID 26841353, 2016). "KIR3DL2-expressing natural killer (NK) cells and IL17 secreting CD4 T cells have been implicated in the pathogenesis of ankylosing spondylitis." (PMID 23162554, 2012). "Furthermore, in ankylosing spondylitis, cumulative evidence indicates ligation of KIR3DL2 on Th17 CD4+ T cells may promote their accumulation and survival." (PMID 39724143, 2024). "Among the KIRs, KIR3DL2, an inhibitory receptor expressed on both NK cells and CD4+ T lymphocytes, plays a critical role in the pathogenesis of ankylosing spondylitis." (PMID 40428751, 2025).
cutaneous T cell lymphoma (5 papers, 2017 to 2024). "Soon, we identified an anti-KIR3DL2 that was subsequently shown to be helpful for the diagnosis and treatment of various forms of cutaneous T cell lymphoma." (PMID 31396241, 2019). "In addition, preliminary clinical studies of a novel targeted immunotherapy for cutaneous T-cell lymphomas using the anti-KIR3DL2 mAb IPH4102 are now underway." (PMID 28912774, 2017).
mycosis fungoides (4 papers, 2017 to 2024). Classical mycosis fungoides is the most common type of mycosis fungoides (MF), a form of cutaneous T-cell lymphoma, and is characterized by slow progression from patches to more infiltrated plaques and eventually to tumors. "Lacutamab, an ICI targeting killer cell immunoglobulin-like receptor 3DL2 (KIR3DL2), was assessed in patients with R/R mycosis fungoides." (PMID 39075582, 2024). "Interestingly, KIR3DL2 expression on T-cells is a marker for several cutaneous T-cell lymphomas as Sésary syndrome and mycosis fungoides." (PMID 35095867, 2021). "In contrast, KIR3DL2 expression is found in several CD4+ T malignancies, including SS, mycosis fungoides (MF) and anaplastic large cell lymphoma (ALCL)." (PMID 29387053, 2017).
malaria (3 papers, 2012 to 2013). Malaria is a serious and sometimes fatal disease caused by a parasite that commonly infects a certain type of mosquito which feeds on humans. "One such study involved analysis of KIR genotypes and in vitro NK cell response to malaria parasite in non-immune donors and reported a relationship between inhibitory KIR3DL2*002 allele and high NK cell IFN-γ response." (PMID 22715396, 2012). "Gene expression levels were greater than two-fold change in acute febrile malaria including: Fc alpha receptor, Fc gamma receptor 3B, Fc epsilon receptor 1G, PI3K, MAP2K2, Arf6, KLRC3, KIR3DL2, and CEBP gamma (range two- to four-fold)." (PMID 24188121, 2013).
HIV-1 infection (2 papers, 2016 to 2022). The type species of lentivirus and the etiologic agent of acquired immunodeficiency syndrome (AIDS). "So far, not much is known about the role of KIR3DL2 in HIV-1 infection but other studies showed also an increased expression of KIR3DL2 in chronic HCV patients and on activated NK cells from patients with spondylarthritis." (PMID 35911762, 2022).
leukemia (2 papers, 2020 to 2023). A malignant (clonal) hematologic disorder, involving hematopoietic stem cells and characterized by the presence of primitive or atypical myeloid or lymphoid cells in the bone marrow and the blood. "However, further investigations are needed to evaluate the role of other inhibitory KIR receptors, such as KIR2DL1, KIR3DL1 and KIR3DL2, in anti-leukemia NK cell responses, particularly against AML." (PMID 32708751, 2020).
lung adenocarcinoma (2 papers, 2021 to 2024). A carcinoma that arises from the lung and is characterized by the presence of malignant glandular epithelial cells. "The analysis revealed a significant downregulation of KIR3DL2 in several tumor types, including lung adenocarcinoma, non-small cell lung cancer, diffuse large B-cell lymphoma, and thymoma." (PMID 39262781, 2024). "The expression levels of IL12A and KIR3DL2 in lung adenocarcinoma, and KIR3DL2 in lung squamous cell carcinoma were significantly lower than in adjacent normal tissues and decreased as the clinical stage increased." (PMID 34943992, 2021).
T cell lymphoma (2 papers, 2012 to 2021). "KIR3DL2 expression is up-regulated on activated CD4 T cells and NK cells in SpA and circulating and T cell lymphoma cells in SS." (PMID 23162554, 2012).
asthma (1 paper, 2022). "Together, these findings suggest a potential biological mechanism either delaying or hastening onset of atopic reactions like hay fever, eczema, or asthma that involves KIR3DL2, and the KIR3DL2*107 and KIR3DL2*062 alleles in particular." (PMID 36002830, 2022).
eczema (1 paper, 2022). "Together, these results suggest that polymorphisms in KIR3DL2 may play a key role in determining the age of onset of hay fever, rhinitis, and/or eczema." (PMID 36002830, 2022). "Moreover, an alternative allele of KIR3DL2, KIR3DL2*062, was weakly associated with an increase in age of onset of hay fever, rhinitis, or eczema from 24.5 years (IQR 12–35 years) to 27.0 years (IQR 14–40 years; Mann-Whitney FDR=0.244)." (PMID 36002830, 2022). "When examining correlations with age of onset of several chronic diseases and conditions, we discovered that KIR3DL2*107 was highly correlated with early age of onset of hay fever, rhinitis, or eczema in Caucasian individuals." (PMID 36002830, 2022).
helminth infections (1 paper, 2021). "Because helminth infections are less prevalent in the populations of industrialized countries, and who provide the subjects for most studies, such studies may not have uncovered a role for KIR3DL2+NK cells in parasitic immunity." (PMID 34760351, 2021).
influenza (1 paper, 2014). An acute viral infection of the respiratory tract, occurring in isolated cases, in epidemics, or in pandemics; it is caused by serologically different strains of viruses (influenzaviruses) designated A, B, and C, has a 3-day incubation period, and usually lasts for 3 to 10 days. "NK cell response related genes such as CD247, KIR2DL4, KIR3DL1, KIR3DL3 and KLRB1 were down-regulated only in moderate and severe patients while genes such as KIR2DL1, KIR2DS4 and KIR3DL2 were down-regulated in all three groups of influenza patients." (PMID 25365328, 2014).
myeloid leukemia (1 paper, 2019). A clonal proliferation of myeloid cells and their precursors in the bone marrow, peripheral blood, and spleen. "The KIR3DL2(+)/HLA-A3/11(-) combination was found significantly more frequently in myeloid leukemia patients than in the healthy population." (PMID 31337191, 2019). "A significantly higher incidence of the KIR3DL2(+)/HLA-A3/11(-) genotype was found in the myeloid leukemia group compared to the healthy control group (AML vs. controls: 88.2% vs. 65.9%, p=0.047, CML vs. controls: 83.3% vs. 65.9%, p=0.047)." (PMID 31337191, 2019). "KIR/HLA class I ligand profile KIR3DS1(+)/L (-) was decreased and KIR3DL2(+)/HLA-A3/11(-) was increased among myeloid leukemia cases compared to controls." (PMID 31337191, 2019). "Thus, the myeloid leukemia-associated genotype KIR3DL2(+)/HLA-A3/11(-) very likely indicates lack of NK cell activity mediated by the inhibitory receptor." (PMID 31337191, 2019).
parasitic infections (1 paper, 2021). "Because the nucleotides flanking CpG motifs in parasitic worm genomes are the least similar to those of the human genome, the correlation between KIR3DL2-DNA binding and parasite genomes may not indicate a role for NK cells in parasitic infections." (PMID 34760351, 2021).
peripheral T-cell lymphoma (1 paper, 2023). "Importantly, the established SS PDX model exhibited a stable immunophenotype and expressed several cell surface targets (ICOS, PD-1, TRBC1 and KIR3DL2) that are currently the subject of early clinical investigation in peripheral T-cell lymphoma." (PMID 37718909, 2023).
spondylitis (1 paper, 2021). The inflammation of a vertebra. "In particular, the aberrant expression of the allele of the HLA B 27 in spondylitis, could act by binding cells that contain a natural killer receptor for HLA B 27 homodimer, named killer cell immunoglobulin-like receptor 3DL2 (KIR3DL2), determining IL-17 production." (PMID 33692806, 2021).
tumor (38 papers, 2013 to 2025). "Consistent with the CNV results, the expression of tumor-associated genes, including KIR3DL2, TOX, TWIST1, and GTSF1, upregulated along the CD4+ T-cell trajectory." (PMID 39963655, 2024). "Notably, there is a significant deficiency of KIR3DL2-highly-expressing NK cells in cluster 0 among HCC patients with tumor recurrence." (PMID 39262781, 2024). "Based on this, the main mode of action of lacutamab in CTCL is currently believed to be a NK cell-mediated ADCC effect on KIR3DL2-expressing tumor T cells." (PMID 38272918, 2024). "Further investigation into the impact of KIR3DL2 on tumor progression led us to conduct a comprehensive study of this molecule using RNA sequencing (RNA-seq) data from multiple datasets of liver tissues." (PMID 39262781, 2024). "Conversely, KIR3DL2 expression on infiltrating NK cells within the tumor tissues of HCC patients was lower compared to their paired adjacent non-tumor tissues." (PMID 39262781, 2024). "Initially, we analyzed the expression of KIR3DL2 across various tumor tissues and their matched normal tissues obtained from TCGA and the Genotype-Tissue Expression (GTEx) databases." (PMID 39262781, 2024). "The findings revealed a significant correlation between KIR3DL2 expression on NK cells in peripheral blood and its expression in both adjacent non-tumor and tumor tissues." (PMID 39262781, 2024). "Based on our findings, we sought to delve deeper into the interactions of NK cells expressing high levels of KIR3DL2, suggesting a quiescent state, with other immune or tumor cells within the tissue microenvironment." (PMID 39262781, 2024). "In the study, we identified an inhibitory receptor belonged to the KIR family, KIR3DL2, which is significantly downregulated in NK cells infiltrating tumor tissues of HCC patients." (PMID 39262781, 2024). "KIR3DL2 expressed on NK and T cells binds to B27-dimers of Face-2, and Face-2 per se on antigen presenting cells, tumor cells, and trophoblast cells." (PMID 37627243, 2023). "CD158k/KIR3DL2 is highly expressed in SS and advanced MF confers resistance to activation induced cell death in SS and has been found efficacious in reducing tumor size and improved survival in vivo and in vitro." (PMID 32039026, 2019). "In vivo efficiency of the anti-tumor activity of IPH4102 was tested in SCID mice engrafted with KIR3DL2-transfected Raji cells." (PMID 28912774, 2017). "The restricted expression of KIR3DL2 in normal immune cells, and the possibility to selectively target the tumor cells in CTCL, led to the development of a humanized mAb for an effective treatment strategy." (PMID 28912774, 2017). "A recent study reported that 87% of a group of SS patients (n = 64) expressed KIR3DL2 (range: 7–98% of tumor T cells) at diagnosis." (PMID 28912774, 2017). "PMBC-derived cells had malignant clones expectedly exhibiting a dominant clonotype (TRBV7-2 and TRAAV2), copy number variations, decreased expression of CD7, and aberrantly elevated expression of KIR3DL2 (CD158k) and CD70, which are known to be tumor-associated." (PMID 40941016, 2025). "It is possible that targeting KIR3DL2 with anti-KIR3DL2 mAbs (aKIR3DL2 mAbs) may not only directly affect tumor T cells but circumvent an important cancer immune-suppressive mechanism by restoring NK cell functions." (PMID 38272918, 2024). "Furthermore, employing single-cell pseudo-temporal analysis via “monocle” revealed that NK cells exhibiting heightened KIR3DL2 expression were positioned in an early differentiation stage among infiltrating NK cells within tumor tissues." (PMID 39262781, 2024). "These outcomes suggest a potential association, indicating that peripheral blood NK cells might serve as a surrogate for evaluating KIR3DL2 expression on NK cells within tumor tissues, offering promise in prognosticating patient outcomes." (PMID 39262781, 2024). "However, a notable correlation was found between KIR3DL2 expression and tumor staging in patients from the ICGC database (p = 0.02)." (PMID 39262781, 2024).